ELK1 (ETS transcription factor ELK1)
Description:
Transcription factor that binds to purine-rich DNA sequences. Forms a ternary complex with SRF and the ETS and SRF motifs of the serum response element (SRE) on the promoter region of immediate early genes such as FOS and IER2. Induces target gene transcription upon JNK and MAPK-signaling pathways stimulation.
Tractability: PROTAC: UniProt records ubiquitination sites on it; ubiquitination databases record sites on it.
Target class: Transcription factor
Gene: Protein-coding gene on chromosome X (47,631,621 to 47,650,604, reverse strand). Ensembl gene ENSG00000126767.
Subcellular location: Nucleus
Subcellular location (Human Protein Atlas): Nucleoplasm
Pathways (Reactome):
Signal Transduction: ERK/MAPK targets; Estrogen-dependent nuclear events downstream of ESR-membrane signaling; NGF-stimulated transcription
Disease: HCMV Early Events
Gene Ontology:
Molecular function: DNA-binding transcription activator activity, RNA polymerase II-specific; DNA-binding transcription factor activity; DNA-binding transcription factor activity, RNA polymerase II-specific; protein binding; RNA polymerase II cis-regulatory region sequence-specific DNA binding; RNA polymerase II-specific DNA-binding transcription factor binding; sequence-specific double-stranded DNA binding; transcription cis-regulatory region binding; chromatin binding; double-stranded DNA binding; mediator complex binding; sequence-specific DNA binding; transcription regulator activator activity; transcription regulator inhibitor activity
Biological process: positive regulation of DNA-templated transcription; positive regulation of transcription by RNA polymerase II; cell differentiation; regulation of transcription by RNA polymerase II; response to fibroblast growth factor; cellular response to gamma radiation; cellular response to lipid; cellular response to testosterone stimulus; hippocampal neuron apoptotic process; regulation of DNA-templated transcription; response to ethanol; response to light stimulus
Cellular component: nucleoplasm; nucleus; chromatin; axon terminus; dendrite; mitochondrial membrane; neuronal cell body
Homologues: Orthologues: chimpanzee ELK1 (99% identical), dog ELK1 (92% identical), pig ELK1 (90% identical), guinea pig ELK1 (89% identical), rabbit ELK1 (86% identical), rat Elk1 (86% identical), mouse Elk1 (86% identical), zebrafish elk1 (51% identical), tropical clawed frog elk1 (44% identical). Paralogues in human: ELK4 (36% identical), ELK3 (35% identical), ERF (21% identical), ETV3 (20% identical), ELF4 (18% identical), ELF1 (17% identical), ERFL (17% identical), ELF2 (16% identical), FEV (16% identical), FLI1 (16% identical), ERG (15% identical), ETV1 (15% identical), and 16 more.
Diseases named in the same sentence as ELK1 in open-access papers:
ELK1 is named in the same sentence as 155 diseases in open-access papers, as found by Europe PMC text mining. Sharing a sentence is not in itself a finding about the gene and the disease. The quoted sentences say what the papers report.
breast carcinoma (51 papers, 2008 to 2025). "ELK1 and pELK-1 expression have been positively associated with several types of cancer, including breast cancer, colonic adenocarcinoma, and prostate cancer." (PMID 30382082, 2018). "In breast cancer specifically, it is implicated in the ELK1/C-Fos pathway." (PMID 30483308, 2018). "Therefore, ELK1 was correlated to mitochondrial dysfunctions, which is a hallmark of cancer, and identified a connecting link between ELK1-mediated transcription and the activity of Breast cancer (BRCA) genes." (PMID 40862737, 2025). "For example, circRNA_0025202 regulates tamoxifen sensitivity and tumorigenesis in breast cancer by modulating the miR-182-5p/FOXO3a axis; as a miR-326 sponge, circ_0000515 promotes cervical cancer progression by upregulating ELK1." (PMID 40426921, 2025). "The vast majority on studies conducted on ELK1’s implications in cancer are about Breast cancer (BC)." (PMID 40862737, 2025). "Suppression of ELK1 inhibits progression of thyroid cancer, pancreatic cancer, breast cancer, and cervical cancer in in vitro and in vivo models." (PMID 38589882, 2024). "ELK1 is upregulated in many other cancers, such as cervical cancer, pancreatic cancer, thyroid cancer, colorectal cancer, and breast cancer." (PMID 38589882, 2024). "We obtained ChIP-seq data of the candidate transcription factors FOSB (ENCSR569XNP), ZNF302 (ENCFF037UPH), SP1 (ENCFF072FPF), ELK1 (ENCFF123KER), and FOXF2 (ENCFF008ABX) in a breast cancer cell line MCF-7 from ENCODE." (PMID 37173692, 2023). "A recent study suggested that ELK1 expression is elevated in a variety of cancers, including breast cancer and lung non-small cell carcinoma." (PMID 33621196, 2021). "Association of MZF1 and Elk1 via the acidic domain of MZF1 and the heparin-binding domain of Elk1 increases invasion, migration and mesenchymal phenotype of breast cancer cells." (PMID 31963147, 2020). "Recent evidence suggests that CXCL5 promotes bone metastasis in breast cancer via the ERK/MSK1/Elk-1/Snail signalling pathway." (PMID 32415115, 2020). "Down-regulation of ELK1 is responsible for the oncogenic role of tumor-suppressive miR-135a in breast cancer." (PMID 31772143, 2019). "Particularly in breast cancer tissues, positive correlations between p-ELK1 expression and AR or estrogen receptor expression were noted." (PMID 26342199, 2015). "In this study, we show that E2 and the selective GPER ligand G-1 up-regulate miR144 expression through the GPER and the involvement of the PI3K/ERK1/2/Elk1 transduction pathway in both breast cancer and hepatocarcinoma cells." (PMID 26030000, 2015). "Elevated expression of ELK1 or p-ELK1 has also been detected in tissue specimens of breast cancer, colonic adenocarcinoma, and lung non-small cell carcinoma." (PMID 26342199, 2015). "The Elk-1 controls cell migration by targeting various genes or by regulating cell survival in breast cancer." (PMID 25326651, 2014). "Previous studies have shown that ERK1/2 can directly phosphorylate and activate many transcription factors including Elk-1 in breast cancer cells." (PMID 23158473, 2012). "Using this method, we demonstrated that cis-regulatory motifs bound by ELK1, E2F, NRF1 and NFY are most significantly associated with breast cancer malignancy." (PMID 18823535, 2008). "Our analysis identified cis-regulatory motifs bound by ELK1, E2F1, NRF1 and NFY as principal motifs associated with breast cancer malignancy." (PMID 18823535, 2008). "In basal-like breast cancer, a 2020 study identified associations between key receptors such as Tumor necrosis factor receptors (TNFRs), Transforming growth factor-beta receptor type 1 (TGFBR1), and EGFR, and ELK1." (PMID 40862737, 2025). "Elk1 seems to be an important mediator of resistance by assisting migration towards growth factors and possibly reinforcing the cells’ ability to survive and proliferate, as has also been shown in breast cancer models." (PMID 40699751, 2025).
breast carcinoma (continued). "The knockdown of ELK1 has reduced pancreatic cancer, breast cancer, and glioblastoma cells." (PMID 38202644, 2023). "Candidate pathways were constructed starting from the estrogen receptor ESR1 gene and targeting breast cancer-associated transcription factors, such as JUN, FOS, STAT1, STAT3, STAT5A, ELK1, and ETS1 (Target transcription factors were pre-identified by GibbsOS19)." (PMID 33432018, 2021). "ELK1 overexpression is frequently observed in many carcinomas, including breast cancer." (PMID 28435519, 2017). "In addition to Snail and p27, approximate 160 substrates of ERK kinase have been identified, many of which are critically involved in breast cancer growth and metastasis, such as c-myc, Elk-1 and MSK." (PMID 26759750, 2016). "Additionally, genome-wide studies in breast cancer cell lines have revealed that ELK1 is involved in the activation of c-Fos, a proto-oncogene that is implicated in tumorigenesis." (PMID 25996148, 2015). "One study showed that chemokine (C-X-C) ligand 5 (CXCL5) could activate Raf/MEK/ERK, MSK1, Elk-1, and Snail, while E-cadherin was down-regulated in breast cancer cell lines." (PMID 25122124, 2014). "In addition, glutathione S-transferase (GST) pull-down assay demonstrated that HIF-2α physically interacts with ETS1, and immunoprecipitation analysis showed that HIF-2α forms a complex with Elk1 in MCF7 (breast cancer) and 786-O (renal cell carcinoma) cells." (PMID 23840432, 2013). "Interestingly, ETS1 and ELK1 have been shown to coordinately upregulate CIP2A, which encodes cancerous inhibitor of protein phosphatase 2A and leads to progression of gastric, cervical and breast cancer." (PMID 32079144, 2020). "These include EMT (TWIST1, SNAIL1, RUNX1, RUNX2, HIF1, and NOTCH1), breast cancer maintenance (OCT4, SP1, GATA1, ATF1, FOXO3a, ELK1, VDR, and NRF1), pro-metastatic responses (SMAD2/3, HNF1a, GLI1, NANOG, YY1, MYB1, and AP1), and immune modulation (STAT1/3)." (PMID 38398186, 2024). "Has_circ_0000515 can sponge miR-326 to promote cervical cancer progression by releasing ELK1 transcription and regulate the miR-296-5p/CXCL10 signalling pathway axis to induce the pathogenesis of breast cancer." (PMID 35155186, 2021). "Motifs bound by ELK1, E2F, NRF1, and NFY positively correlate with malignant progression of breast cancer." (PMID 30486409, 2018). "ELK1 is a member of the ETS TF family, which is closely related to various disorders, including Alzheimer’s disease, Down syndrome and breast cancer, in a dose-dependent manner." (PMID 29780667, 2018). "Elk1 and CIP2A showed higher mRNA expression in tumor versus adjacent normal tissue from all breast cancer patient samples, from paired tumor/normal tissue and from the TNBC subpopulation." (PMID 26824320, 2016). "We observed a positive correlation between moderate-to-strong PKCα and either Elk-1 and/or MZF-1 staining in breast cancer." (PMID 27542222, 2016). "In contrast, in breast cancer MCF-7 cells expressing an AR as well as estrogen receptors, ELK1 overexpression reduced their colony formation." (PMID 26342199, 2015). "Importantly, we have confirmed the role of ELK1 in controlling cell migration in several human breast-derived epithelial cell lines, and it is possible that ELK1 may play a role in cellular metastasis in the context of breast cancer." (PMID 22589737, 2012). "Our analysis found that motifs bound by ELK1, E2F, NRF1 and NFY are potential regulatory motifs that positively correlate with malignant progression of breast cancer." (PMID 18823535, 2008). "Knockdown of ELK-1, a member of the Ets family of transcription factors, significantly reduced hypoxic induction of the HIF-2α target genes, including CITED2, WISP2, and IGFBP3 in MCF-7 breast cancer cells." (PMID 30478339, 2018).
breast carcinoma (continued). "In addition, Elk-1 has been reported to upregulate the expression of death receptor 5 (DR5), a transmembrane receptor that triggers the extrinsic apoptotic pathway, in breast cancer and lung cancer." (PMID 30267330, 2018). "To determine whether the clinical relevance of the correlation between PKCα and Elk-1 and/or MZF-1 exists in breast cancer, we examined the expression of these proteins in tissue arrays by immunohistochemical (IHC) staining." (PMID 27542222, 2016). "Here, we demonstrate that in SkBr3 breast cancer and HepG2 hepatocarcinoma cells, 17β-estradiol (E2) and the selective GPER ligand G-1 induce miR144 expression through GPER and the involvement of the PI3K/ERK1/2/Elk1 transduction pathway." (PMID 26030000, 2015). "In the present study, we show that in SkBr3 breast cancer and HepG2 hepatocarcinoma cells E2 and G-1 induce the expression of miR144 and down-regulate the levels of Runx1 through GPER and the involvement of the PI3K/ERK1/2/Elk1 transduction pathway." (PMID 26030000, 2015). "However, GPER1 can activate additional mediators of cell survival, such as extracellular signal-related kinase 1 and 2 (ERK1/2), ELK1, CREB, and FOS that may be involved in IGFBP-3 induction upon Ful treatment in breast cancer cells." (PMID 39619437, 2024). "Interestingly, a complex formation between Elk-1 and MZF1 has been shown to enhance PRKCA expression in a synergistic manner and its expression correlates positively with the expression of Elk1 and MZF1 in various breast cancer cell lines." (PMID 31963147, 2020). "ELK1, but not SRF or STAT3, was reported to regulate both the basal and epidermal growth factor induced MCL1 transcription in breast cancer cells." (PMID 40075071, 2025). "However, the knockdown of the other three transcription factors (ELK1, GTF2I and FOXP3) did not reduce UBE2T expression levels in breast cancer cells." (PMID 36338541, 2022). "Moreover, we propose that Snail may promote EMT in breast cancer cells possibly through activation of p-ERK and preferentially the ERK2 isoform and not the ERK1 isoform since MCF-7 Neo cells have high levels of p-ERK1 that does not activate Elk-1 activity." (PMID 25122124, 2014).
cervical carcinoma (28 papers, 2014 to 2025). A carcinoma arising from either the exocervical squamous epithelium or the endocervical glandular epithelium. "We evaluated ELK1, a low peak group TF, across three biologically diverse cell lines using cross-validation: HeLa-S3 (cervical carcinoma, 6091 peaks), K562 (chronic myelogenous leukemia, 3793 peaks), and GM12878 (B-lymphoblastoid, 7245 peaks)." (PMID 41294241, 2025). "The overexpression of miR-130b-5p functioned as a tumor suppressor in cervical cancer by targeting ELK1, diminishing the self-renewal capacity of cervical cancer stem cells and lowering the expression of stemness-associated proteins (OCT4, Sox2, and Nanog)." (PMID 40710326, 2025). "The circular RNA hsa_circRPPH1_015 was found to act by sponging miR-326, which is a known suppressor of ELK1 expression in cervical cancer as well." (PMID 40862737, 2025). "In cervical cancer (CC), several recent studies have explored the role ELK1 in tumorigenesis and progression, especially through the scope of RNA regulation." (PMID 40862737, 2025). "In cervical cancer (CC) tissues, the expression of miR-130b-5p is diminished, while the expression of its target gene ELK1 is elevated." (PMID 40710326, 2025). "A previous study exhibited that transcription factors YY1 and ELK1 bound to the miR-320-3p promoter and increased miR-320-3p expression in cervical cancer and colon cancer cells." (PMID 35054986, 2022). "For example, in cervical cancer increased miR-130b-5p was shown to downregulate the transcription factor ELK1 which resulted in decreased stemness, proliferation and migration of cervical cancer cells." (PMID 35597813, 2022). "Circle RNA has-circ-0000515 was reported to upregulated the expression of ELK1 functioning as a miR-326 sponge to promote cervical cancer development." (PMID 33682613, 2021). "For example, a circular RNA acts as the miR-326 sponge to enhance the progression of cervical cancer via increasing ELK1 expression." (PMID 33534779, 2021). "For instance, high level of hsa_circ_0000515 acts as a tumor promoter in cervical cancer through miR-326/ELK1 axis." (PMID 31911754, 2020). "Previous study proves that miRNA-326 restrains the growth and aggressiveness of cervical carcinoma cell by mediating ETS Transcription Factor ELK1 (ELK1)." (PMID 32425696, 2020). "Western blot and RT-qPCR were conducted to measure ELK1 expression in cervical cancer cells, which showed that ELK1 expression was lower in cervical cancer cells transfected with si-hsa_circ_0000515 or miR-326 mimic, versus those with si-NC or mimic NC." (PMID 31772143, 2019). "More importantly, miR-326 has been found to impede proliferative, migrating and invasive capabilities by targeting ELK1 in cervical cancer." (PMID 31772143, 2019). "The expression of ELK1 in cervical cancer tissues was increased when compared to the normal adjacent tissues (p < 0.05)." (PMID 31772143, 2019). "hsa_circ_0000515 and ETS transcription factor ELK1 (ELK1) were initially over-expressed and miR-326 was down-regulated in cervical cancer tissues and cells." (PMID 31772143, 2019). "Compared with the normal group, ELK1 expression was the highest compared to the rest of the genes, which were mildly elevated in cervical cancer tissues." (PMID 31772143, 2019). "A series of mimics, inhibitors, over-expression plasmids or siRNAs were introduced into cervical cancer cells to alter the expression of hsa_circ_0000515, miR-326 and ELK1." (PMID 31772143, 2019). "The study demonstrated the hsa_circ_0000515/miR-326/ELK1 network in the carcinogenesis of cervical cancer, which highlights potential novel targets for cervical cancer treatment." (PMID 31772143, 2019). "In line with our data that ELK1 over-expression promoted cervical cancer development, ELK1 is also able to inhibit the suppressive effects of Tanshinone I on proliferation of HeLa cells." (PMID 31772143, 2019).